ATF3 (activating transcription factor 3)
Diseases named in the same sentence as ATF3 in open-access papers (continued):
Sharing a sentence is not in itself a finding about the gene and the disease.
breast cancer (continued). "Thirdly, ATF3 is known to be strongly involved as both tumor suppressor and an oncogene in breast cancer cells, and was proposed as potential therapeutic target in breast cancer treatment." (PMID 26537518, 2015). "Although ATF3 has been well known to promote metastasis in the breast cancer, ATF3 expression can induce apoptosis in human breast cancer cells (MCF-7 and MDA-MB-231)." (PMID 25494848, 2014). "On the other hand, ATF3 induces DNA synthesis and expression of cyclin D1 in hepatocellular carcinoma cells and enhances cancer cell-initiating features in breast cancer." (PMID 25338635, 2014). "ATF3 is both tumor suppressive in early stage tumorigenesis and oncogenic in late stage tumorigenesis in breast cancer cell lines." (PMID 25494848, 2014). "ATF3 was observed in the nuclei of breast cancer cells and typically appeared as buffy granulo-staining." (PMID 24494067, 2013). "This study investigated the expression and clinical significance of activating transcription factor 3 (ATF3) in human breast cancer and its relationship with the clinical outcome of breast cancer." (PMID 24494067, 2013). "Materials and Methods: ATF3 expressions were detected in 114 primary breast cancer tissues and 114 adjacent normal tissues using immunohistochemistry (IHC) assay." (PMID 24494067, 2013). "It is now necessary to elucidate the relationship between ATF3 and breast cancer based on the results of previous studies." (PMID 24494067, 2013). "The difference in ATF3 expression between breast cancer and adjacent normal breast tissues was statistically significant (P=0.009)." (PMID 24494067, 2013). "Elevated ATF3 expression has been reported in human breast cancers as protective against apoptosis or as promoting metastasis of cancer cells." (PMID 23533526, 2013). "In the present communication, we have provided several lines of evidence that the canonical Wnt/β-catenin pathway is activated in BK5.ATF3 mammary tumors." (PMID 21304988, 2011). "IHC analysis indicated robust expression of Snail protein (the product of Snai1) in ATF3-induced mammary tumors." (PMID 21304988, 2011). "In the present study, we show that the Wnt/β-catenin pathway is functionally activated in mammary tumors induced in the BK5.ATF3 model." (PMID 21304988, 2011). "In ATF3-induced mammary tumors, overall expression of β-catenin appeared to be stronger than in normal tissue, and clear localization to the nuclei of tumor cells was widespread." (PMID 21304988, 2011). "The ATF3-induced mouse tumors are phenotypically similar to mammary tumors induced by overexpression of activating Wnt/β-catenin pathway genes." (PMID 21304988, 2011). "In a previous study, similarities were noted between the histopathology of ATF3-induced mammary tumors and lesions described in several transgenic models in which the Wnt/β-catenin pathway is upregulated." (PMID 21304988, 2011). "These phenotypic similarities suggested the possibility that the Wnt/β-catenin pathway is somehow activated in ATF3-induced mammary tumors, or alternatively that ATF3 is a downstream effector of Wnt/β-catenin signaling." (PMID 21304988, 2011). "The SNAI2 and SNAI1 genes have recently been identified as direct transcriptional targets of ATF3 in human mammary cells, and the murine homologs, Snai2 and Snai1 are up-regulated in ATF3-induced mammary tumors." (PMID 21304988, 2011). "This transgenic mouse model system reproduces some features of human breast cancer in that about 20% of human breast tumor specimens exhibit overexpression of ATF3 in the tumor cells." (PMID 21304988, 2011). "Female transgenic mice that constitutively overexpress the transcription factor ATF3 in the basal epithelium of the mammary gland develop mammary carcinomas with high frequency, but only if allowed to mate and raise pups early in life." (PMID 21304988, 2011).
breast cancer (continued). "Western blotting further showed upregulation of BiP and activating transcription factor 3 (ATF3) in nelfinavir-treated breast cancer cells, indicating induction of endoplasmic reticulum stress." (PMID 20594311, 2010). "Overexpression of ATF3 in CK5-expressing cells of the murine mammary gland results in the development of squamous metaplastic lesions in nulliparous females, and in mammary tumors in biparous mice, suggesting that ATF3 acts as a mammary oncogene." (PMID 18808719, 2008). "Mammary tumor incidence reached 67% within the biparous BK5.ATF3 group (blue triangles) by 12 months of age." (PMID 18808719, 2008). "Analysis of ATF3-induced mammary tumors revealed widespread expression of CK10 in 10 of 10 tumors examined." (PMID 18808719, 2008). "Essentially all cells in the suprabasal layers of the BK5.ATF3 mammary tumors clearly expressed CK6 (arrows)." (PMID 18808719, 2008). "Further analysis of the BK5.ATF3 mammary tumors revealed deeper anomalies in cytokeratin expression that are not easily explained solely by mammary stem cell origin." (PMID 18808719, 2008). "Over 90% (13 of 14 tumors examined) of the mammary tumors that developed in parous BK5.ATF3 female animals showed significant nuclear expression of ERα." (PMID 18808719, 2008). "Thus, this study attempts to provide a comprehensive understanding of the emphasis of ATF3 in invasive hypoxic breast cancer cells." (PMID 40016181, 2025). "Therefore, we investigated if PKM2 has any role in the induction of ATF3 in hypoxic breast cancer cells." (PMID 40016181, 2025). "Injection of breast cancer cells into ATF3-transgenic mice also increased breast cancer metastasis." (PMID 38279150, 2024). "Low expression of ATF3 is closely related to poor prognosis in breast cancer patients." (PMID 38244591, 2024). "They discovered that highly metastatic breast cancer cells had much lower levels of ATF3 expression than less metastatic cells, indicating that ATF3 may play a role in limiting breast cancer cell metastasis." (PMID 38046946, 2023). "ATF3 has been widely reported in the treatment of diseases, such as prevention of cardiac hypertrophy and fibrosis, neuronal axon regeneration after traumatic nerve injury, liver fibrosis treatment, and breast cancer target." (PMID 37889831, 2023). "It has been demonstrated that when CTLA-4+ breast cancer cells and human dendritic cells (DCs) are cocultured, the extracellular signal-regulated kinase and activating transcription Factor 3 (ATF3) of DCs are inhibited, thus suppressing the function and maturation of DCs." (PMID 37860188, 2023). "At the individual gene level and compared to controls, ATF3-induced mammary tumors exhibited reduced expression of Rb1, Esr1, and Pgr, and increased expression of Erbb2, Egfr, and the genes encoding keratins 5, 6, and 17, which is similar to basal-like human breast cancer tumors." (PMID 33652981, 2021). "To determine whether ATF3 directly affects expression of MIR145/143 in human breast cancer cells, we generated an shRNA knockdown system to experimentally manipulate ATF3 levels in MDA-MB-157 cells." (PMID 33652981, 2021). "MDA-MB-157 is a triple-negative human breast cancer cell line that expresses high levels of ATF3." (PMID 33652981, 2021). "We tested whether expression of either Klf4 or Sox2 was affected in BK5.ATF3 mammary tumors using RT-qPCR and found that both Klf4 and Sox2 were significantly upregulated (p < 0.005) in tumors with lower MiR145 levels." (PMID 33652981, 2021). "Mammary tumors in BK5.ATF3 mice express cytokeratins characteristic of both the luminal (Krt8) and myoepithelial (Krt5) differentiation pathways, suggesting that stem or bipotent progenitor cells may be the target for malignant transformation in this model." (PMID 33652981, 2021).
breast cancer (continued). "Notably, 50–80% of human breast cancers express high levels of the bZip transcription factor ATF3, and ATF3 mRNA levels increase when adult cells are exposed to stress signals, such as those produced in response to DNA damage or other cellular stress." (PMID 33652981, 2021). "In breast cancer, ATF3 is involved in regulating the proapoptotic effect of chemotherapeutic drugs." (PMID 33315500, 2021). "We used FOXP3-Tet-off MCF7 cells to evaluate whether FOXP3 affects ATF3 protein expression since MCF7 (human breast cancer) cells express very small amounts of FOXP3." (PMID 34768829, 2021). "ATF3 is a potent oncogene that is aberrantly expressed in most human breast cancers." (PMID 33652981, 2021). "Additionally, elevated expression of ATF3 has been correlated with poor overall survival in breast cancer, even though in a cohort skewed towards the lobular carcinoma subtype." (PMID 33050633, 2020). "The ATF3 gene is amplified and increased in human breast cancer." (PMID 32922364, 2020). "ATF3 KO mice show less efficient breast cancer metastasis than WT mice." (PMID 32922364, 2020). "As ATF3 is an adaptive-response gene and has a dichotomous role in breast cancer cells in a context-dependent manner, the detailed mechanism whether ATF3 is involved in super-enhancer-driven RCAN1.4 expression should be clarified in the further study." (PMID 32771023, 2020). "Furthermore, downstream Wnt/β-catenin target genes, including CCND1, Jun, Axin2, and Dickkopf 4 (Dkk4), are upregulated in mammary tumors in BK5.ATF3 mice." (PMID 32922364, 2020). "In line with our findings, ATF3 has been mostly characterized as an oncogene in breast cancer." (PMID 33050633, 2020). "The canonical Wnt/β-catenin pathway is activated in BK5.ATF3 mammary tumors." (PMID 32922364, 2020). "In conclusion, throughout the research, ATF3 expression could exert significant influences on various spheres of the breast cancer radioresistance that is the efficiency of radiation therapy." (PMID 30117642, 2018). "Knockdown of ATF3 expression in breast cancer cells decreases cell migration." (PMID 30237810, 2018). "ATF3 gene was able to promote radioresistance of breast cancer cells." (PMID 30117642, 2018). "In addition, ATF3 attenuated the effect of irradiation in vivo (P < .05), while silence of ATF3 enhanced the sensitivity of irradiation of breast cancer (P < .05)." (PMID 30117642, 2018). "ATF3 is reported to work as a regulator in myeloid cells that enhances breast cancer metastasis." (PMID 29534690, 2018). "Therefore, the following experiment was focused on the relationship between ATF3 expression and radioresistance of breast cancer." (PMID 30117642, 2018). "Previous study found that the expression of miR-590 was down regulated in human breast cancer and this could be regulated by ATF-3." (PMID 29534690, 2018). "ATF3 was observed stronger in breast cancer tissues and cells." (PMID 30117642, 2018). "After the analysis of ATF3 expression level in different cell lines, it was found out that the mRNA expression level of ATF3 was also remarkably higher in breast cancer cell lines T47D, ZR751, MCF7, HBL100 and SUM159 than that in normal human mammary epithelial cell line MCF10A (all P < 0.05)." (PMID 30117642, 2018). "Previous study indicated that the transcription of miR-590 could be inhibited by ATF-3.Then we detected the function of ATF-3 on regulating the proliferation of breast cancer cells." (PMID 29534690, 2018). "The results suggested that ATF3 could augment the radioresistance of breast cancer cells by affecting the related proteins expressions in the PI3K/Akt signalling pathway." (PMID 30117642, 2018).
breast cancer (continued). "Furthermore, the transgenic overexpression of ATF3 in the mammary epithelium activates the canonical Wnt/β-catenin pathway and mammary tumor formation." (PMID 29966001, 2018). "Finally, ATF3 which was strongly expressed in multiple breast cancer cell samples were chosen for next experiments." (PMID 30117642, 2018). "After radiation therapy, the expression of ATF3 in breast cancer cells was up‐regulated." (PMID 30117642, 2018). "The strong up-regulation of the Activating transcription factor 3 (ATF3) (16.8-fold) associated to EndoR stress and the abrogation of the apoptotic response after ATF3 silencing suggests this protein as a potential molecular target for γ-tocotrienol in breast cancer cells." (PMID 29156559, 2017). "However, the expression level of the CREB family member Activating Transcription Factor 3 (ATF3) was significantly reduced in TTP-low breast cancer, lung adenocarcinoma and colon adenocarcinoma." (PMID 25541715, 2014). "This indicated that ATF3 might be involved in the tumorigenesis, invasion and metastasis of breast cancer, inferring that ATF3 might be a new tumor marker for breast cancer patients." (PMID 24494067, 2013). "Further studies on a large scale should be performed, and they might support the idea that ATF3 is useful as either a biomarker or therapeutic target of breast cancer, since breast cancer has been recognized as a heterogeneous disease." (PMID 24494067, 2013). "Up to now, to the best of our knowledge, the relationship and molecular mechanisms of ATF3 in the progression and metastasis of breast cancer remain unclear." (PMID 24494067, 2013). "Phenotypically, mammary tumors induced in the BK5.ATF3 model resemble tumors and dysplastic lesions that have been reported in several transgenic models in which components of the Wnt/β-catenin pathway are overexpressed and the pathway is thereby constitutively activated." (PMID 21304988, 2011). "Interestingly, immunoprecipitation of mammary tumor extracts with ATF3-specific antiserum, followed by immunoblotting demonstrated significant intracellular association between ATF3 and Jun proteins." (PMID 21304988, 2011). "Two genes, Wnt1 and Wnt 5b, were significantly down-regulated in ATF3-induced mammary tumors." (PMID 21304988, 2011). "For instance, Yin and co-workers have demonstrated in in vitro experiments that ATF3 induces apoptosis in non-malignant mammary epithelial cells, but reduces apoptosis and enhances motility in breast cancer cells, suggesting an oncogenic role of ATF3 in breast cancer." (PMID 21129190, 2010). "For instance, ATF3 can mediate pro-apoptotic effects in human mammary epithelial cells, whereas in breast cancer cells (MCF10A) it may promote cell survival, motility and invasiveness." (PMID 21129190, 2010). "However, it is still unclear whether TXNIP, SLC2A1, and ATF3 affect the growth of breast cancer cells by regulating the ferroptosis mechanism." (PMID 38244591, 2024). "ATF3 could promote the apoptosis of T-cell lymphoma, multiple myeloma, colon cancer cells, and endometrial cancer cells, while the overexpression of ATF3 promoted the metastasis of breast cancer and prostate cancer." (PMID 34966780, 2021). "Additionally, overexpression of ATF3 also enhances radioresistance of breast cancer." (PMID 34098867, 2021). "This implied that Atf3 might play a role in human breast cancer." (PMID 30373101, 2018). "On the contrary, if ATF3 expression in breast cancer cells was silenced by the siATF3 transfection or was suppressed by the signalling pathway inhibitor LY204002, breast cancer radioresistance could be relieved to a great extent and the radiation therapy efficiency can be also improved." (PMID 30117642, 2018).
breast cancer (continued). "When ATF3 expressed highly in breast cancer, the cancer radioresistance was enhanced and radiation therapy could not well function in causing breast cancer cell apoptosis or in remaining the G2/M phase cell cycle block." (PMID 30117642, 2018). "Furthermore, ATF3 activates the canonical Wnt/β-catenin pathway in human breast cancer cell." (PMID 25494848, 2014). "Thus, the further elucidation of mechanisms for ATF3 role involved in EAFAD-B-induced apoptosis may be needed in human breast cancer and hepatocellular carcinoma cells." (PMID 25494848, 2014). "Indeed, ATF3 appears to play distinct roles in different tissues: ATF3 acts as a tumour suppressor in colorectal cancer while it is oncogenic in prostate cancer, mammary cancer, skin cancer, and Hodgkin's lymphoma." (PMID 22046379, 2011). "Significant differences were observed in breast cancer tumour staging for ALOX5, ALOXE3, ALOX12, and ATF3 genes." (PMID 38516826, 2024). "Downregulation of SLC2A1 expression promoted ferroptosis and suppressed tumor cell growth in breast cancer cells (P < 0.01), while overexpression of TXNIP or ATF3 had the same effect (P < 0.01)." (PMID 38244591, 2024). "ATF3 is overexpressed in breast cancer cells treated with PTX, and XAP reverses the effects of PTX on ATF3." (PMID 38957318, 2024). "ATF3 elevation, in turn, stimulates increased expression of ABCB1 efflux pumps resulting in enhanced tamoxifen efflux conferring the breast cancer cells' resistance to this drug." (PMID 39661414, 2024). "Here, we have shown that ATF3-induced mammary tumors in BK5.ATF3 mice have gene expression characteristics similar to both human BLBC and other “basal-like” mouse models of mammary cancer." (PMID 33652981, 2021). "We performed RNA-Seq analysis on single mammary tumors from each of three parous, transgenic BK5.ATF3 mice, along with matched normal, adjacent, mammary gland tissue from the same transgenic mice." (PMID 33652981, 2021). "ATF-3 is highly upregulated and its expression level is maintained by TGF-ß1 in highly invasive/metastatic human breast cancer (MDA-MB231)." (PMID 32922364, 2020). "In turn, ATF3, by repressing miR-590-3p expression, modulates the miR-590/GOLPH3 signaling pathway to promote proliferation of breast cancer cells." (PMID 32023813, 2020). "ATF3 is upregulated by cisplatin and carboplatin in lung cancer cells (A549), human ovarian cancer cells (SKOV-3, A2780-cp), breast cancer cells (MCF-7) and prostate cancer cells (PC3)." (PMID 32922364, 2020). "In summary, our results demonstrated the ATF-3/ miR-590-3p/GOLPH3 signaling pathway on regulating the proliferation and the cell cycle of breast cancer cells." (PMID 29534690, 2018). "The transcription factor ATF3 acts as an oncogene in mouse mammary gland and enhances TGFβ signaling and CSC features in breast cancer cell lines." (PMID 25414831, 2014). "In contrast, ATF3 overexpression enhanced transcription of FN (fibronectin)-1, TWIST (twist transcription factor)-1 and Slug in MCF10CA1 breast cancer cells, and led to increased proliferation of DU145 prostate cancer cells." (PMID 22768301, 2012). "Thus we have reason to believe that further analysis of the BK5.ATF3 model, in which mammary tumors are clearly basal-like and exhibit activated Wnt/β-catenin signaling, may provide a better understanding of processes that are extremely important in human breast tumorigenesis." (PMID 21304988, 2011). "For these experiments, we utilized a mouse mammary cancer cell line, EMT6, in which we found robust expression of the endogenous Atf3 gene in preliminary experiments." (PMID 21304988, 2011). "The results revealed that breast cancer tissues exhibited lower expression levels of SAT1, ALOX5, ALOX12, ATF3, ATF4, GPX4 and NFE2L2 compared to normal tissues; conversely, higher expression levels of ALOX15, ALOXE3 and HO‐1 were observed in breast cancer tissues than in normal tissues." (PMID 38516826, 2024).